IL6 (interleukin 6)
Diseases named in the same sentence as IL6 in open-access papers (continued):
Sharing a sentence is not in itself a finding about the gene and the disease.
schizophrenia (continued). "The CSF levels of IL-6 were significantly correlated with the levels of IL-6 in plasma within the total study population (P<0.001) and in patients with recent onset of schizophrenia alone (P=0.03)." (PMID 27070405, 2016). "STRING analysis highlighted first-order protein interactions among IL12RB1 and IL12B, IL1B, IL6, and IL12A, all of which have previously been associated with schizophrenia." (PMID 27746755, 2016). "It is important to the field to present multiple lines of consistent data regarding elevated levels of IL-6 in participants with schizophrenia in independent cohorts." (PMID 27206977, 2016). "In keeping with our findings a meta-analysis of serum cytokine alterations in schizophrenia or related psychotic disorder patients found increased levels of interleukin, among those IL6, IL12, TNF-α, TGF-β although with significant heterogeneity." (PMID 27650124, 2016). "IL-6 has been proposed to act as a “state marker” for schizophrenia, with elevated serum levels seen in first episode psychosis and acutely relapsed patients." (PMID 27206977, 2016). "Maternal immune activation models of neurodevelopmental insults have heralded insight into the role of IL-6 and schizophrenia." (PMID 27206977, 2016). "Serum IL-6 was significantly higher in schizophrenia patients in comparison with healthy controls (median: 1.4 ± 2.23 and 1.07 ± 0.77, respectively, p = 0.049)." (PMID 25214388, 2015). "The first meta-analysis of cytokine alterations in schizophrenia patients provided that IL-6 level is increased in this group of patients." (PMID 25214388, 2015). "Altered levels of IL-6 in the cerebrospinal fluid have been found in patients with schizophrenia and ASD." (PMID 26633355, 2015). "Apart from playing a central role in ADT-induced NED, IL-6 has recently come to attention as a key player in the pathogenesis of schizophrenia." (PMID 25785244, 2015). "We have found a positive correlation between IL-6 level and illness duration along with significantly higher levels of IL-6 in schizophrenia patients with chronic course of the disorder with deterioration." (PMID 25214388, 2015). "Serum IL-6 positively correlated with hsCRP in schizophrenia patients (r = 0.57, p < 0.001) and healthy controls (r = 0.52, p < 0.001)." (PMID 25214388, 2015). "Correlations between serum IL-6 level, illness duration and course of the disorder are in line with the notion that schizophrenia is a progressive disorder with low-grade inflammation, underlying its pathophysiology followed by cognitive decline." (PMID 25214388, 2015). "Serum IL-6 and hsCRP levels were significantly higher in schizophrenia patients in comparison with healthy controls." (PMID 25214388, 2015). "Our first time observations suggest a significant relationship between IL-6 rs1800795 and reduced hippocampal volume in antipsychotic-naïve schizophrenia." (PMID 24787542, 2014). "Various lines of evidence including epidemiological, genetic and foetal pathogenetic models suggest a compelling role for Interleukin-6 (IL-6) in the pathogenesis of schizophrenia." (PMID 24787542, 2014). "In a previous study that used Next Generation Sequencing Expression, IL-6 mRNA was increased in the PFC of patients with schizophrenia, suggesting an increase in inflammation in the schizophrenic PFC." (PMID 24886351, 2014). "Mounting evidence indicates that in other neuropsychiatric conditions such as schizophrenia, inflammatory cytokines such as IL-1β and IL-6 have a role in onset and progress of neuropsychiatric symptoms." (PMID 25344730, 2014). "This view is also underscored by human disease findings of elevated cytokines in schizophrenia and autism, as well as the critical role of IL-6 in maternal immune activation models." (PMID 25374324, 2014). "There is evidence of immune dysfunction in patients with schizophrenia as reflected by increased proinflammatory cytokine, such as interleukin 6 (IL-6)." (PMID 22704639, 2012).
schizophrenia (continued). "Dysregulated expression of IL-6 has been documented in several neurological disorders such as MS, acute transverse myelitis, Alzheimer’s disease, schizophrenia, epileptic seizures, and Parkinson’s disease." (PMID 22524232, 2012). "Additionally, increased concentrations of IL-1β, IL-6, IL-10, IL-17, and sIL-2, and a reduction in TNF-α are associated with more severe positive symptoms of schizophrenia." (PMID 40364201, 2025). "The significant interaction validates our subgroup analyses of elevated plasma IL-6 levels associated with the severity of depressive symptoms in individuals with early schizophrenia only, but not in those with established schizophrenia." (PMID 39911538, 2025). "Support for immune dysregulation has been provided by meta-analyses that have consistently shown that peripheral IL-6 levels are mildly increased in individuals with schizophrenia at the early and established stages as well as in individuals with MDD compared with healthy control participants." (PMID 39911538, 2025). "Notably, animal research has revealed that elevated levels of interleukin 6 (IL-6) during gestation induce schizophrenia-like symptoms in offspring, which can be mitigated by anti-IL-6 antibodies." (PMID 41303622, 2025). "Elevated levels of IL-6 in the serum are associated with more severe negative symptoms in patients with schizophrenia and other psychoses." (PMID 39858450, 2025). "In the combined sample of early and established schizophrenia and in early schizophrenia only, the interrelationship between higher plasma IL-6 levels, structural brain metrics, and general cognitive performance did not significantly predict more severe depressive or negative symptoms." (PMID 39911538, 2025). "Using data from Early-stage (BeneMin) and Established (iRELATE) cohorts, we found that higher plasma IL-6 levels were associated with more severe depressive symptoms in Early schizophrenia and more severe negative symptoms in Established schizophrenia." (PMID 39911538, 2025). "We applied SEM to assess the relationships of plasma IL-6 levels, CT and volume of 8 ROIs, and general cognitive performance to depressive and negative symptom severity in individuals with early and established schizophrenia." (PMID 39911538, 2025). "Furthermore, a positive correlation between the total PANSS score and increased concentrations of IL-1β, sIL-2R, IL-13, IL-6, and IL-17 in chronic patients with schizophrenia was found." (PMID 40364201, 2025). "However, excessive IL-6 expression can exacerbate neurological disorders such as autism, schizophrenia, and Alzheimer’s disease by promoting immune-driven inflammation." (PMID 40276707, 2025). "In addition, a number of clinical trials have shown that the administration of olanzapine to patients with schizophrenia causes an increase in plasma cytokines like TNF-α, IL-6, and IL-1." (PMID 38292473, 2024). "An early study found that IL-1β, IL-6 and TNF-α could inhibit cortical neuronal dendritic development and possibly increase the risk of schizophrenia." (PMID 39831058, 2024). "Interestingly, IL-6 affects brain structure and contributes to neuropsychiatric disorders like schizophrenia." (PMID 39202552, 2024). "In the context of schizophrenia, researchers have found evidence of cytokines such as C-reactive protein (CRP), IL-1β, IL-6, IL-12, interferon-γ, and tumor necrosis factor α (TNF-α) being associated with endophenotypes and varying disease status of schizophrenia." (PMID 38445386, 2024). "IL-6 is one of the most extensively studied cytokines in schizophrenia research to date." (PMID 38979494, 2024). "Levels of P-selectin correlated positively with levels of S100B and IL-6, and it was postulated that in patients with schizophrenia, peripheral immune activation may be related to neuro-inflammation and the activation of astrocytes." (PMID 39858403, 2024). "Elevated IL-6, changes in cytokines, and neuroinflammation are found in schizophrenia patients." (PMID 39816323, 2024).
schizophrenia (continued). "Evidence suggests that the variability of IL-6 levels is significantly reduced compared to healthy controls, indicating that elevated IL-6 levels may be a key factor in the immune phenotype of schizophrenia." (PMID 38979494, 2024). "Also, another meta-analysis with a large scale of 59 studies found first-episode patients (FEP) with schizophrenia have higher levels of IL-6 and TNF-α than the general population." (PMID 38352871, 2024). "In the context of examining neuroinflammation in chronic schizophrenia, a separate study unveiled elevated IL-6 levels in individuals with persistent schizophrenia, accompanied by heightened concentrations of various cytokines, including TNF-α, IL-12, INF-γ, and sIL2r." (PMID 39273641, 2024). "Therefore, this study attempts to establish associations between serum cytokines IL-6, IL-12, IL-5, IL-10 and TGF-β1 changes and the effectiveness of ECT in treatment-resistant schizophrenia patients." (PMID 39595201, 2024). "Hence, in this study, we aimed to compare the serum IL-6 levels between TRS patients and patients with treatment-responsive schizophrenia and explore potential sex differences in the association of TRS and IL-6 levels." (PMID 37370004, 2023). "•Microglia IL-6 transcriptome overlaps with schizophrenia post-mortem genesets." (PMID 36781081, 2023). "IL-6 is the most well-known cytokine related to schizophrenia." (PMID 37644489, 2023). "However IL-6 is considered a state cytokine marker of schizophrenia, and increased IL-6 levels have been found in various phenotypes of schizophrenia (e.g., FEP)." (PMID 37370004, 2023). "Particularly at the onset of schizophrenia and during the recurrence of psychotic episodes, blood levels of proinflammatory cytokines such as IL-1β, IL-6, and TNF-α tend to increase, and levels of IL-6 are associated with poor schizophrenia prognosis." (PMID 37371435, 2023). "Pro-inflammatory serum cytokines including IL-6 and IL-17 are elevated in patients after with schizophrenia pharmacological treatment, and have been shown to be deregulated in treatment-resistant schizophrenia." (PMID 37032951, 2023). "Furthermore, aside from BDNF, other inflammatory factors such as IL-6 and TNF and the complement system are associated with neurodevelopment and schizophrenia, and their correlation analysis with the age of young children needs to be investigated further." (PMID 37234686, 2023). "Schizophrenia studies have found higher IL-6 levels in the CSF than in the blood and lower IL-1β CSF levels compared to those in the blood, as well as lower levels of IL-1β, IL-6, and TNF-α and higher IL-8 levels in the CSF than in the blood of MDD subjects." (PMID 37510730, 2023). "Our finding of elevated IL-6 in schizophrenia is consistent with multiple previous studies." (PMID 37239308, 2023). "Emerging studies have shown that sex differences in IL-6 may also occur in patients with schizophrenia." (PMID 37370004, 2023). "Moreover, several studies found an increase in cytokines levels, including IL-6 and IL-10 in suicidal victims (Schizophrenia Working Group of the Psychiatric Genomics Consortium, 2014)." (PMID 37183855, 2023). "A neuroinflammatory response translates into the activation of microglia, which increases the production of cytokines, especially interleukin 6 (IL-6), the increase of which is evident in patients during the first episode or in the acute relapse of schizophrenia." (PMID 37373704, 2023). "PUFAs reduce neuroinflammation and, in patients with schizophrenia, result in a reduction in proinflammatory cytokines, such as IL-6 and TNF-α; a reduction in CRP; and an increase in BDNF, which, due to its neurotrophic action, has positive effects on cognition function." (PMID 37371435, 2023). "Importantly, the IL-10/IL-6 ratio was lower in the SZ group, which indicates the predominance of pro-inflammatory processes in schizophrenia." (PMID 37239308, 2023).
schizophrenia (continued). "Indeed, increased IL-6, TNF-α, and other pro-inflammatory cytokines have been consistently implicated in psychiatric disorders, specifically, ASD, schizophrenia, and bipolar disorders." (PMID 37355708, 2023). "Human postmortem studies carried out on individuals diagnosed with schizophrenia, brain samples showed lower tlr4 mRNA and protein levels, and downregulation of il6, il10, and tnfa mRNA in the prefrontal cortex (PFC) region, and elevated TLR4 protein levels in the cerebellum region." (PMID 37627253, 2023). "For instance, a single maternal injection of IL-6 on day 12.5 of mouse pregnancy causes pre-pulse inhibition (PPI) and latent inhibition (LI) deficits in the adult offspring, mimicking central features of schizophrenia." (PMID 35495047, 2022). "In the adult human brain, we found that IL-6 may form an interacting community with other proteins differentially overexpressed in the MTG, including CCK and NPY, which are also implicated in schizophrenia and other mental illnesses." (PMID 35353173, 2022). "Among pro-inflammatory cytokines, the levels of interleukin (IL)-1α, IL-6, IL-11, IL-12A, IL-15, IL-17A, and granulocyte colony-stimulating factor (G-CSF) in tears were significantly higher in patients with schizophrenia than that in normal controls (all P < 0.01)." (PMID 35223927, 2022). "We found that IL-6 did not significantly differ between high and low inflammation individuals or between controls and patients in our cohort at the transcriptional level, but IL-6 does typically appear to be elevated at the protein level in people with schizophrenia." (PMID 35027554, 2022). "Furthermore, a specific point mutation of the DISC1 gene (L100P) interacts with MIA during gestation, resulting in an exacerbated phenotype of schizophrenia probably mediated by IL-6." (PMID 35963926, 2022). "This study included 45 DSCZ and 45 NDSCZ patients and 40 controls and delineated whether the IL-6/IL-23/Th17 axis, trace elements (copper, zinc) and ions (magnesium, calcium) are associated with DSCZ, the G-CoDe and the schizophrenia phenome." (PMID 36256663, 2022). "Maes and colleagues emphasized IL-6 as a biomarker for treatment-resistant schizophrenia." (PMID 35337097, 2022). "The presence of abnormally high levels of pro-inflammatory cytokines such as Tumor Necrosis Factor alpha (TNF-α) and Interleukin 6 (IL-6) found in schizophrenia patients indicates that in some patients it is possible that the immune system balance is being tipped toward a more inflammatory state." (PMID 35844244, 2022). "By inference, the strong effects of the IL-6/IL-23/Th17 axis on both the cognitive detrioration and symptomatome of schizophrenia indicate that IL-23, Th17, IL-22 and IL-21 may further contribute to the neurotoxic effects." (PMID 36256663, 2022). "In addition, our results were consistent with previous studies that people with FES and a confirmed diagnosis of schizophrenia had elevated IL-6 levels in their peripheral blood and cerebrospinal fluid (CSF)." (PMID 36590607, 2022). "Therefore, it is likely that elevated FcGR3A contributes to the pattern of increased levels of IL-1β, IL-6, and TNFα in the midbrain which can be used to define the high-inflammation biotype of schizophrenia." (PMID 35841099, 2022). "These events, along with NETs production, are likely to contribute to the release of inflammatory cytokines, such as IL-6, which together could contribute to stress-related neurobiological changes seen in schizophrenia." (PMID 36572669, 2022). "The first study, an 8-week randomized, double-blind, placebo-controlled, parallel, fixed-dose pilot clinical trial in 12 patients with schizophrenia, showed that 300 mg of curcumin add-on to conventional medication significantly improved working memory and reduced interleukin-6 (IL-6) levels." (PMID 35204235, 2022).
schizophrenia (continued). "Moreover, increased neurotoxicity caused by increased levels of toxic cytokines (e.g., IL-1β, IL-6, IL-8, TNF-α, and IFN-γ) and chemokines (e.g., CCL11, CCL2, CXCL8, and CXCL10) is significantly associated with the G-CoDe and the schizophrenia phenome." (PMID 36256663, 2022). "IL-1β, which can induce the conversion of rat mesencephalic progenitor cells into a dopaminergic phenotype, and IL-6, which decrease the survival of fetal brain serotonergic neurons, both significantly influence the neurotransmitter systems involved in schizophrenia." (PMID 35963926, 2022). "And IL-6 was evaluated in the schizophrenia group (p < 0.001)." (PMID 34025476, 2021). "Changes in water anisotropy within the white matter fibers (which may be associated with altered white matter quality and lead to disturbances in connections between different areas of the brain) may correlate with IL-6 levels in patients with schizophrenia." (PMID 34501305, 2021). "Maternal infections during pregnancy that increased IL-1 β, IL-6, and TNF-α levels in their offspring, hypothesized to be LPS-induced, increased susceptibility to schizophrenia." (PMID 34220440, 2021). "Finally, a meta-analysis shows decreased circulating IL6 levels after antipsychotic treatment in schizophrenia patients." (PMID 34911938, 2021). "Taken together, these results suggest that IL-6 combined with QA might contribute to neuronal damage in the brain in schizophrenia." (PMID 34393855, 2021). "Abnormal maturation and microglia activation could be associated with elevated levels of IL-6 and TGF-β in the course of schizophrenia." (PMID 34501305, 2021). "IL-6 is closely related to PANSS-P scores in patients with schizophrenia." (PMID 34305669, 2021). "Elevated IL-6 serum levels are strongly correlated with schizophrenia." (PMID 34220440, 2021). "Schizophrenia has also been shown to be associated with polymorphisms of numerous genes responsible for the synthesis of such cytokines as IL1A, IL1B, IL10 and IL6, which are genes for, respectively, IL-1α, IL-1β, IL-10 and IL-6." (PMID 34501305, 2021). "Third, we show that the previously reported protective effect of CRP on schizophrenia could be explained by IL-6, an upstream inducer of CRP production." (PMID 34280516, 2021). "Furthermore, postmortem studies indicate increased mRNA levels of IL-1β and IL-6 in schizophrenia as well as in bipolar disorder patients." (PMID 33976392, 2021). "Therefore, this study aimed to investigate the serum level of inflammatory markers (CRP and IL-6) among patients with schizophrenia." (PMID 34465310, 2021). "IL-6 is reported raised in subjects with at-risk mental state (ARMS) and might be a marker of transition from ARMS to schizophrenia." (PMID 33746786, 2021). "This pattern of results indicates that CRP, and hence IL-6 classic signalling, is unlikely to be the main “causal driver” of schizophrenia risk." (PMID 34280516, 2021). "Uric acid serum levels could be associated with IL-6 elevation in exacerbation, once more showing IL-6 as a crossroads in the pathophysiology of schizophrenia." (PMID 35237183, 2021). "One meta-analysis showed that acutely relapsed patients with schizophrenia have increased levels of peripheral interleukins (IL) including IL-6, IL-8, tumor necrosis factor alpha (TNF-α), interferon gamma (IFN-γ) but reduced levels of IL-10 when compared with healthy controls." (PMID 33667853, 2021). "Further clinical studies have found increased biomarkers of neuroinflammation in schizophrenia patients, including greater levels of circulating inflammatory cytokines such as Interleukin-6 (IL-6), Tumour Necrosis Factor Alpha (TNF-α) and Interferon Gamma (IFN-γ)." (PMID 34366935, 2021). "Indeed, increased cerebrospinal fluid (CSF) concentrations of interleukin (IL)-6 is found in chronic schizophrenia and increased CSF IL-1β in first-episode schizophrenia." (PMID 33976392, 2021).